PLSCR5 (phospholipid scramblase family member 5)
Tractability: Antibody: its Gene Ontology location is reachable by antibodies, with medium confidence.
Gene: Protein-coding gene on chromosome 3 (146,576,555 to 146,605,346, reverse strand). Ensembl gene ENSG00000231213.
Gene Ontology:
Molecular function: phospholipid scramblase activity
Biological process: plasma membrane phospholipid scrambling
Cellular component: plasma membrane
Genetic constraint (gnomAD): Loss-of-function variants: 38 observed, 24.12 expected, observed/expected ratio (o/e) 1.58, 90% interval 1.21 to 1.92. The synonymous counts are far from expectation, so gnomAD's model fits this gene poorly and the ratio says little. Missense variants: 334 observed, 280.65 expected, observed/expected ratio (o/e) 1.19, 90% interval 1.09 to 1.3. Synonymous variants: 140 observed, 101.22 expected, observed/expected ratio (o/e) 1.38, 90% interval 1.21 to 1.59.
Homologues: Orthologues: chimpanzee PLSCR5 (99% identical), macaque PLSCR5 (94% identical), rabbit PLSCR5 (92% identical), dog PLSCR5 (91% identical), pig PLSCR5 (90% identical), mouse Plscr5 (88% identical), guinea pig PLSCR5 (88% identical), rat Plscr5 (88% identical), tropical clawed frog PLSCR5 (57% identical), zebrafish si:ch73-206p6.1 (48% identical), zebrafish si:ch211-71m22.1 (47% identical), zebrafish si:ch211-71m22.5 (45% identical), and 4 more. Paralogues in human: PLSCR1 (55% identical), PLSCR2 (51% identical), PLSCR3 (44% identical), PLSCR4 (39% identical).
Diseases named in the same sentence as PLSCR5 in open-access papers:
PLSCR5 is named in the same sentence as 1 disease in open-access papers, as found by Europe PMC text mining. Sharing a sentence is not in itself a finding about the gene and the disease. The quoted sentences say what the papers report.
autoimmune disease (1 paper, 2020). A disorder resulting from loss of function or tissue destruction of an organ or multiple organs, arising from humoral or cellular immune responses of the individual to their own tissue constituents. "These links to both autoimmune disease and blood clotting, as well as the well-described role of phospholipase scramblases in externalizing procoagulant PS, suggest that further study of the role of PLSCR5 in the complex pathogenesis of canine IMHA is warranted." (PMID 33091028, 2020).